RN7SL339P (RNA, 7SL, cytoplasmic 339, pseudogene)
Gene: Miscellaneous RNA gene on chromosome 5 (171,359,117 to 171,359,412, forward strand). Ensembl gene ENSG00000265740.
Homologues: Orthologues: chimpanzee Metazoa_SRP (79% identical), macaque Metazoa_SRP (72% identical), macaque Metazoa_SRP (64% identical). Paralogues in human: Metazoa_SRP (81% identical), Metazoa_SRP (78% identical), RN7SL774P (78% identical), RN7SL474P (78% identical), RN7SL811P (78% identical), RN7SL123P (77% identical), RN7SL134P (77% identical), RN7SL622P (77% identical), RN7SL96P (77% identical), RN7SL154P (77% identical), RN7SL784P (77% identical), RN7SL391P (76% identical), and 708 more.